PTH (parathyroid hormone)
Diseases named in the same sentence as PTH in open-access papers (continued):
Sharing a sentence is not in itself a finding about the gene and the disease.
Obesity (continued). "This suggests that obesity-related hyperphosphatemia may play a role in metabolic bone disease and cardiovascular calcification beyond the effects of PTH alone." (PMID 40136609, 2025). "Parathyroid hormone (PTH) dysregulation is commonly seen in obesity." (PMID 40136609, 2025). "Plausible mechanisms through which vitamin D might contribute to obesity include parathyroid hormone (PTH) and vitamin D receptor (VDR)." (PMID 40077674, 2025). "Vitamin D, calcium, and PTH: The functions of vitamin D and PTH in obesity are heavily debated." (PMID 40585599, 2025). "While SG is effective in improving metabolic outcomes and reducing obesity-related comorbidities, it may affect various aspects of nutritional and metabolic health, including calcium (Ca) metabolism, vitamin D levels, and parathyroid hormone (PTH) secretion." (PMID 39553143, 2024). "Studies have suggested that low vitamin D levels may influence adipose tissue differentiation and growth, impacting obesity through gene expression regulation or by modulating parathyroid hormone (PTH), calcium, and leptin." (PMID 38032745, 2024). "The patients have hyperphagia and obesity but only mild brachydactyly and PTH resistance." (PMID 39104441, 2024). "However, the relationship between serum calcium and PTH is left-shifted in obesity, making the interpretation of the clinical significance of high PTH levels challenging." (PMID 36703643, 2023). "Other studies have shown a correlation between obesity and bone marrow fat and PTH activity." (PMID 36936115, 2023). "The obesity-driven increase in PTH could give rise to an increase in intracellular calcium and a proportional decrease in extracellular calcium—preventing the purported action of calcium on blood pressure and increasing vascular resistance." (PMID 38075210, 2023). "The relationship between vitamin D and PTH levels in obesity is complex." (PMID 36291463, 2022). "Low serum 25(OH)D has been associated with elevated parathyroid hormone (PTH) and low intracellular Ca2+, which may contribute to obesity due to elevated lipogenesis and suppressed lipolysis." (PMID 33801275, 2021). "On the other hand, a reduced level of circulating 25(OH)D could by itself contribute to obesity development by inducing increased parathyroid hormone levels and the important inflow of calcium into adipocytes, resulting in lipogenesis and/or adipogenesis." (PMID 34445049, 2021). "Low 25(OH)D levels, balanced by increased PTH concentrations, characterize people with obesity." (PMID 34071985, 2021). "A retrospective study of 316 patients in a Spanish hospital found that neither 25(OH)D nor PTH was associated with obesity after adjusting for potential confounding factors." (PMID 34531372, 2021). "Nevertheless, whether PTH is an independent predictive factor in the development of obesity or would be mediated by 25 (OH) D is still a debate." (PMID 34322512, 2021). "Network analysis showed that obesity could inhibit 11 MI promoters and activate one potential MI regulator (PTH)." (PMID 33842562, 2021). "This limits the interpretation of the results since obesity is known to increase PTH levels." (PMID 32148490, 2020). "Secondary elevation of PTH has been postulated as an independent predictor of obesity." (PMID 31164629, 2019). "Children with obesity may be defended against consequences of low 25(OH)D concentration by keeping lower levels of PTH secretion; therefore, they may need a lower 25(OH)D concentration for the maintenance of bone metabolism and calcium homeostasis." (PMID 31770397, 2019). "Obesity status-associated IR may induce high circulating intact (iFGF-23) and C-terminal FGF-23 (CtFGF-23), which is positively associated with PTH and negatively associated with vitamin D, resulting in low bone mass." (PMID 23983685, 2013). "Some studies reported more important role of PTH than vitamin D in obesity and metabolic syndrome." (PMID 22363895, 2012).
Obesity (continued). "A patient with typical clinical manifestations of pseudohypoparathyroidism (PHP) (round face, short stature, centripetal obesity, brachydactyly, and multi-hormone resistance: parathyroid hormone (PTH), thyroid-stimulating hormone (TSH), and gonadotropins) presented at our center." (PMID 21822432, 2011). "Other authors have hypothesized that the long term suppression of PTH may instead hold the key to obesity prevention." (PMID 22254043, 2010). "Furthermore, pathways such as parathyroid hormone synthesis, secretion, and action, and choline metabolism in cancer were also significantly altered, reflecting broader metabolic disturbances related to obesity." (PMID 39594072, 2024). "Related studies suggest elevated PTH and obesity may also impact VD’s biological effects." (PMID 38794718, 2024). "PTH can influence lipid levels through its effects on calcium and activation of vitamin D in the kidney, but it can have some more direct effects on insulin resistance, adipose tissue metabolism, lipolysis, and obesity development, as well as lipid metabolism in the liver." (PMID 38412162, 2024). "We first examined whether exogenous PTH affects the development of obesity." (PMID 36060945, 2022). "Furthermore, PTH itself could favor obesity by increasing intracellular calcium concentrations, which in turn seems to promote triglycerides accumulation and inhibit lipolysis." (PMID 33670644, 2021). "Therefore, lower PTH levels are expected to be associated with lower BMI in subjects without obesity." (PMID 34580590, 2021). "However, the dose of vitamin D supplementation for the suppression of parathyroid hormone levels may differ in adults with overweight and obesity." (PMID 33206192, 2020). "They speculated that the relation between 25(OH)D and PTH may be altered in obesity." (PMID 29489840, 2018). "This means, a clear tendency to show low calcidiol levels and increased PTH levels in severe obesity in relation to other nutritional situations is detected; in this way, other authors have highlighted that this condition might constitute a metabolic and/or cardiovascular risk factor." (PMID 28287628, 2017). "It is also plausible that depressed 25 (OH) D and elevated PTH levels might also play a role in the development of obesity as there are known physiological mechanisms through which depressed 25 (OH) D and/or PTH elevations promote the accumulation of adipose tissue." (PMID 27275291, 2015). "In addition, suppression of parathyroid hormone (PTH) by 25[OH]D supplementation could have a beneficial effect in obesity." (PMID 25632374, 2013). "In the Scandinavian Obesity Surgery Registry (SOReg), 550 primary RYGB patients, with eGFR > 60 mL/min/1.73 m2, had PTH and 25-OH D levels registered at 10 years." (PMID 39865206, 2025). "Three RCTs have investigated the effects of vitamin D fortification on various health biomarkers, including blood pressure (BP), blood lipids, parathyroid hormone (PTH) levels, and indicators of obesity." (PMID 39770943, 2024). "Additionally, obesity is a risk factor for cancers in at least 13 sites in humans, and obesity has been associated with increased dietary phosphate and elevated serum levels of hormones that regulate Pi metabolism: fibroblast growth factor 23 (FGF23) and parathyroid hormone (PTH)." (PMID 38392693, 2024). "Some groups have shown a positive correlation between parathyroid hormone (PTH) and body mass index (BMI) or duration of obesity." (PMID 38202014, 2023). "In addition, we did not measure the parathyroid hormone (PTH) status that might have helped to better explain the association between vitamin D status and obesity." (PMID 34620118, 2021). "It is mainly characterized by resistance to PTH and TSH, and by peculiar clinical features such as short stature, obesity, cognitive impairment, subcutaneous ossifications and brachydactyly." (PMID 33663571, 2021).
Obesity (continued). "The purpose of this study was to investigate the association of bone mineral density (BMD) with serum vitamin D levels, parathyroid hormone (PTH), calcium, obesity, and bone turnover markers in Palestinian postmenopausal women." (PMID 28124221, 2017). "Obesity positively regulates osteoclasts functioning by upregulating the synthesis of RANKL, TNF-α, MCP1, IL-6, PTH and M-CSF while also downregulating ERα expression, thereby accelerating bone resorption." (PMID 27746742, 2016). "PHP1A comprises patients affected with resistance to PTH and TSH (and other GPCR proteins), and features of obesity and Albright hereditary osteodystrophy including short stature, brachydactyly, ectopic ossifications and mental retardation." (PMID 26583054, 2015). "Other variables, including obesity, smoking, biochemical derangements (albumin, calcium, phosphorus, triglycerides, cholesterol), left ventricular ejection fraction, and parathyroid hormone, were not independently predictive after adjustment." (PMID 41267729, 2025). "Additionally, the implications of elevated parathyroid hormone (PTH) and its relationship with lipogenesis and obesity are discussed." (PMID 39439522, 2024). "GNAS variants were recently described in 1% of patients not known to have pseudohypoparathyroidism/inactivating PTH/PTHrP signalling disorder 2 in the UK Genetics of Obesity Study." (PMID 39104441, 2024). "The mother of the proband had short fingers but showed no PTH resistance, round face, or signs of obesity." (PMID 36669868, 2023). "PTH treatment slightly decreased the body weight of DIO mice and did not affect the daily food intake, indicating a potential prophylactic effect of PTH on diet-induced obesity." (PMID 36060945, 2022). "Women with obesity showed lower levels of vitamin D (O: 17.27 (7.85) ng/mL, NoO: 24.51 (9.60) ng/mL; p < 0.01), and higher levels of PTH (O: 53.24 (38.44–65.96) pg/mL, NoO: 35.24 (25.36–42.40) pg/mL; p < 0.01)." (PMID 35458178, 2022). "This is in keeping with the possible explanation that the activation of PTH axis in obesity happens with much lower levels of vitamin D compared to normal." (PMID 31176378, 2019). "Previous studies, however, have demonstrated that the relationship between serum 25(OH)D levels and obesity is independent of serum PTH levels." (PMID 24466233, 2014). "Descriptive statistics of all study participant serum samples tested for Bone Panel (osteoprotegrin (OPG), leptin, parathyroid hormone (PTH) and insulin), Matrix Metalloproteinase Panel (MMP-2, MMP-8, MMP-9) and Obesity Panel (adiponectin and C-reactive protein (CRP))." (PMID 23577067, 2013). "Descriptive statistics of all study participant saliva samples tested for Bone Panel (osteoprotegrin (OPG), leptin, parathyroid hormone (PTH) and insulin), Matrix Metalloproteinase Panel (MMP-2, MMP-8, MMP-9) and Obesity Panel (adiponectin and C-reactive protein (CRP))." (PMID 23577067, 2013). "Although the most-studied and best-known function of vitamin D, together with parathyroid hormone (PTH), is related to bone metabolism, many studies show evidence of the relationship between obesity and low levels of 25(OH)D (the best indicator of clinical levels of vitamin D)." (PMID 23228198, 2012). "The authors found no seasonal variance in PTH compared to lean children and argued that obesity might be a confounding factor." (PMID 38750418, 2024). "However, a previous study suggested that there exists a relationship between obesity and high PTH levels independent of the vitamin D status." (PMID 34580590, 2021). "In addition, PTH levels in patients with obesity correlated significantly positively to fat mass, but not significantly to weight or BMI z-score." (PMID 31164629, 2019). "The racial disparity of PTH among boys aged 13–17 could not be explained by low birth weight and current obesity of the Black youth." (PMID 26176843, 2015).
Obesity (continued). "However, the racial difference in PTH among boys aged 13–17 was not explained by their obesity and low birth weight status." (PMID 26176843, 2015). "On the other hand, our previous study and other studies have demonstrated that insulin resistance and obesity have a negative effect on serum levels of 25-hydroxyvitamin D [25 (OH) D] and a positive effect on parathyroid hormone (PTH) concentrations in the women with PCOS." (PMID 27141540, 2015). "However, measurement of PTH may be of additional value in children in whom VDD is clinically suspected or in situations when vitamin D concentrations may be unreliable, such as in children with obesity." (PMID 34100559, 2021). "Interestingly, PTH is positively correlated with BMI and total FM, suggesting a functional effect of VDD in obesity that warrants treatment with vitamin D supplementation; chronic excess PTH can lead to insulin resistance and has been hypothesised to promote adipogenesis." (PMID 31089772, 2020).
anemia (128 papers, 2006 to 2026). A reduction in the number of red blood cells, the amount of hemoglobin, and/or the volume of packed red blood cells. "The fibrosis production in the bone marrow caused by increased PTH adversely affects erythroid progenitor cells, thus exacerbating anemia in CKD patients." (PMID 40244253, 2025). "The mechanisms suggested by researchers are as follows: iron deficiency, inflammation, and the raised parathyroid hormone (PTH) level also contribute to causing anemia." (PMID 36815007, 2023). "As for ESRD patients, anemia and serum albumin and parathyroid hormone level had been demonstrated to be associated with CI (Herrmann, Safran, Levkoff, & Minaker, 1992; Stivelman, 2000), which is similar to our study." (PMID 31985179, 2020). "Previous studies have shown that the serum PTH level is independently associated with the LVH, with the decline of PTH, the anemia alleviated, and the nutrition condition improved, and the toxicity of PTH receded." (PMID 33187492, 2020). "In conjunction to PTH assay the serum vitamin D assay should also be taken into account, that has been found to be associated to a decrease of hemoglobin and presence of anemia in CKD-patients." (PMID 25113067, 2015). "Simultaneous achievement of dialysis dosage, anemia, and serum albumin targets was associated with a marked reduction in mortality and other studies extend these observations to include serum calcium, phosphorus, and PTH targets." (PMID 34620096, 2021). "Parathyroid hormone has been associated to anemia in the past." (PMID 25113067, 2015). "Intact PTH is a significant uremic toxin that may cause long-term effects, such as renal osteodystrophy, severe vascular calcifications, cardiovascular structure and function changes, immunological dysfunction, and anemia." (PMID 39791168, 2025). "Third, the modest sample sizes limited statistical power for detailed subgroup/stratified analyses (e.g., by ESRD etiology, comorbidity profiles, or anemia/mineral‐bone disorder markers such as hemoglobin and PTH)." (PMID 41552885, 2026). "This study aimed to assess toxic element levels in adults undergoing hemodialysis compared to a control group and to investigate the correlation between parathyroid hormone (PTH) levels, uremic pruritus, anemia and toxic element concentrations." (PMID 40278557, 2025). "The prevalence of nutrient deficiencies for ferritin (12–20%), folic acid (19–27%), vitamin D (24–31%) and zinc (57–76%) as well as anemia (19–26%) and elevated PTH levels (61–77%) increased after SADI-S." (PMID 40343655, 2025). "Herein, we investigated the hematinic status (vitamin B12, folate, iron, ferritin), 25(OH)D-calcium status, anemia markers, and PTH levels as well as the frequency of MNDs before and 12 months following LSG." (PMID 39771007, 2024). "Parathyroidectomy in uremic patients has improved the hematocrit levels due to an increase in serum concentration of immunoreactive erythropoietin which is an indirect piece of evidence of the correlation of PTH with anemia in ESRD patients." (PMID 36815007, 2023). "It is evident from the literature that, among ESRD patients, the overproduction of PTH leads to changes in mineral and bone composition, eventually resulting in anemia." (PMID 36815007, 2023). "We describe a patient with a modest elevation in PTH who had reversible transfusion‐dependent anemia in the setting of reversible bone marrow changes when management of his SHP was optimized." (PMID 35846199, 2022). "Lymph#, Neu#, RDW-CV, PLT, NLR, PLR, ALP, PTH, and other related indicators can quickly and accurately detect the values of blood, in order to effectively indicate abnormalities of infection, anemia, and cruor." (PMID 36187616, 2022). "Poorly controlled SHP, indicated by elevated parathyroid hormone (PTH) levels, is often associated with severe anemia." (PMID 35846199, 2022).